IL13 (interleukin 13)
Diseases named in the same sentence as IL13 in open-access papers (continued):
Sharing a sentence is not in itself a finding about the gene and the disease.
asthma (continued). "Significant heterogeneity of T-cell phenotypes was observed, with levels of IL-13–secreting T cells and type 2 cytokines increased at some, but not all, asthma severities." (PMID 25746968, 2015). "In summary, HDAC2 gene expression and enzyme activity might be suppressed in patientswith asthma, resulting in NF-κB activation and increased BAL levels of IL-8, IL-5,IL-13, GM-CSF, and TNF-α." (PMID 25923460, 2015). "They found that gene signature profiles of Th2 (IL-13, IL-4) and Th17 (CXCL1, CXCL2, CXCL3, IL-8, CSF3) immune responses were inversely correlated in these samples suggesting a reciprocal regulation of these two pathways in asthma." (PMID 26561853, 2015). "In the development of asthma, allergen-specific CD4+ T cells play a pivotal role by facilitating airway inflammation, which is largely mediated by type 2 T-helper (Th2) cytokines such as interleukin 4 (IL-4), IL-5 and IL-13." (PMID 26488300, 2015). "The sputum inflammatory mediator profiles were distinct with increased TH2 (IL-5, IL-13, and CCL26) and TH1 mediators (CXCL10 and 11) in severe asthma compared with COPD and increased IL-6, CCL2, CCL3, and CCL4 in COPD compared with severe asthma." (PMID 25129678, 2015). "It is known that the significant elevations in IL-13 are found in the airways of patients with both allergic and nonallergic asthma." (PMID 27275233, 2015). "Th2-type cytokines, including IL-4, IL-5, IL-13, IL-17, and IL-33 produced by activated CD4+ T-cells, enhance IgE production, eosinophil accumulation, and play a central role in the pathogenesis of asthma." (PMID 26385707, 2015). "In addition to Th2 cells that produce IL-4, IL-5, and IL-13, double IL-4- and IL-17-expressing memory CD4+ T cells were detected in severe asthmatic patients and in lungs of mice developing experimental asthma." (PMID 26284078, 2015). "Furthermore, consistent with the increased recognition that epithelial cells play a fundamental role in asthma pathogenesis, it is notable that STAT6 expression in lung epithelial cells was shown to be exclusively required for IL-13-mediated pathology." (PMID 24587331, 2014). "Absence of Th2 cytokines IL4, IL-5 and IL-13 was also detected in school children (median age 12 years) with severe treatment-resistant asthma regardless of bronchial eosinophilia." (PMID 25905006, 2014). "To determine the role of Abl in smooth muscle in the production of cytokine and chemokine, we evaluated the level of IL-13 and CCL2 (representative cytokine and chemokine in asthma pathology) in the BALF in lungs of naïve and OVA-treated Abl-lox and Ablsm−/− mice." (PMID 24112389, 2013). "They did not see significant differential methylation of IL13 between asthmatic and non-asthmatic children but asthma-related traits were not tested and also the interaction with genetic variants was not examined." (PMID 24314122, 2013). "Thus, IL-4/IL-13/signal transducer and activator of transcription 6 (STAT6) pathway becomes promising targets for asthma therapies by using IL-4 receptor antagonists and anti-IL-13 mAbs." (PMID 24204835, 2013). "Attempts to validate importance of IL-13 in human asthma revealed that only 50% of individuals with asthma had elevated IL-13 levels in sputum, irrespective of the severity of the disease." (PMID 24032029, 2013). "After adjustment for age, sex, parental history of asthma, parental history of atopy, in utero exposures to maternal smoking, ETS, dampness, incense burning, pet ownership at home and community, IL-13 SNPs showed statistical significance for the occurrence of wheeze (FDR<0.05)." (PMID 23382814, 2013). "This is exemplified by the ability of only IL-4 to differentiate naïve CD4+ T cells into Th2 cells or the non-redundant role of IL-13 in parasite expulsion, allergic inflammation and asthma." (PMID 23027612, 2012).
asthma (continued). "In the GCE-induced asthma model, intranasal administration of GCE increased airway hyperresponsiveness (AHR), inflammatory cell infiltration, productions of serum immunoglobulin E, interleukin (IL)-5, IL-13 and TNF-α production in alveolar macrophages." (PMID 23094102, 2012). "The Th2 cytokines IL-4 and IL-13 also seem to play a role in asthmatic inflammation, but therapies targeting IL-5, IL-4, or IL-13 have provided little or no relief of asthma symptoms and little relief from airways hyperresponsiveness." (PMID 23150736, 2012). "In summary, administration of SCTE in this mouse asthma model significantly decreased the number of eosinophils in BALF and lung tissue, and reduced IL-4 IL-5, IL-13, TNF-α, and eotaxin production in BALF and total IgE and OVA-specific IgE levels in plasma after OVA challenge." (PMID 23244755, 2012). "Interleukin (IL)-13, IL-4, interleukin 4 receptor (IL-4Ra), signal transducer and activator of transcription 6 (STAT6) and tumor necrosis factor-alpha (TNFα) genes are key inflammatory genes in the development of allergic diseases such as asthma." (PMID 22355322, 2012). "It is not surprising therefore that anti-IL-13 proved to be disappointing in asthma therapy given that only half of the patients recruited to a given clinical trial have any likelihood of responding to this biologic." (PMID 23189057, 2012). "However, other studies have demonstrated significant differences in IL-13 level in induced sputum and airway mucosa, as well as in the levels of certain chemokines (such as CXCL8 and CXCL10) in BALF between EB and asthma." (PMID 22839528, 2012). "Th2 cytokines, IL-4, IL-5 and IL-13 produced by activated CD4+ T cells, play a central role in the pathogenesis of asthma by controlling the key process of immunoglobulin E (IgE) production, growth of mast cells and the differentiation and activation of mast cells and eosinophils." (PMID 22514638, 2012). "CD4+ T helper type 2 (TH2) cells, their cytokines IL-4, IL-5 and IL-13 and the transcription factor STAT6 are known to regulate various features of asthma including lung inflammation, mucus production and airway hyperreactivity and also drive alternative activation of macrophages (AAM)." (PMID 22014099, 2011). "Airway eosinophilia, together with Th2 cytokines IL-4, IL-5 and IL-13, may ultimately contribute to AHR in asthma." (PMID 21695271, 2011). "Wyeth has another monoclonal antibody against human IL-13, IMA-026 that is in phase II clinical trials after completion of phase I investigation on allergen-induced late asthma responses in subjects with mild asthma (NCT00725582)." (PMID 23283176, 2011). "The NK-1R antagonist WIN62577 inhibited ASMC IL-13-induced proliferation and ASMC migration in vitro and therefore may be a new therapeutic option in asthma." (PMID 21777465, 2011). "There was a significant interaction between asthma and gender for IL-2-stimulated accumulation of IL-13+ T cells (p = 0.003) but not IFN-γ+ T cells (p = 0.42)." (PMID 20667106, 2010). "The purpose of this study was to define the role of oxytocin in modulating human airway smooth muscle (HASMCs) function in the presence and absence of IL-13 and TNFα, cytokines known to be important in asthma." (PMID 20670427, 2010). "The pharmacology of neutralising anti-IL-13 monoclonal antibodies (mAb) has been investigated in experimental models of asthma in mice, sheep and non-human primates." (PMID 20957211, 2010). "Although IL-13 appears to be central to the pathogenesis of airway fibrosis in asthma and in some animal models of interstitial fibrosis, other models of lung fibrosis are not dependent on Th2 inflammation and IL-13." (PMID 20738867, 2010). "CD3+CD28-stimulated accumulation of IL-13+ T cells was also greater in female subjects, but was not influenced by asthma status." (PMID 20667106, 2010).
asthma (continued). "Thus, the evidence suggests that the balance of IL-13 and IFN-γ levels in the airway is important in determining the levels of local 15-LO-1 expression and the severity of airway inflammation in asthma." (PMID 20953328, 2010). "Despite these promising results, the clinical approaches towards asthma therapy by neutralizing IL-4, IL-5, or IL-13 frustrated the high expectations or did not progress to clinical trials." (PMID 20976014, 2010). "Increased accumulation of both IL-13+ and IFN-γ+ in asthmatics contradicts the Th2 hypothesis of asthma, yet is consistent with observations of IFN-γ being elevated (with type 2 cytokines) in some asthmatics." (PMID 20667106, 2010). "Compared with the control (no IL-13), IL-13 treatment significantly decreased ADRB2 mRNA expression in bronchial epithelial cells from asthma and COPD patients." (PMID 20470412, 2010). "Following stimulation there was a significant increase in the expression of IL-13 in CD3+ T cells in asthma (p = 0.02), but not in patients with EB or healthy controls." (PMID 19602238, 2009). "We sought to examine IL-13 expression in peripheral blood T-cells and eosinophils in asthma and non-asthmatic eosinophilic bronchitis." (PMID 19602238, 2009). "Peripheral blood CD3+ cell and eosinophil intracellular IL-13 expression from subjects with asthma, non-asthmatic eosinophilic bronchitis and healthy controls was assessed." (PMID 19602238, 2009). "We have shown that in asthma IL-13 expression is increased in peripheral blood T cells, but not eosinophils compared to subjects with EB or healthy subjects." (PMID 19602238, 2009). "In asthma interleukin (IL)-13 is increased in the airway compared with non-asthmatic eosinophilic bronchitis." (PMID 19602238, 2009). "Blocking IL-13, but not IL-4, in animal models of asthma prevents the development of airway hyperresponsiveness after allergen, despite a strong eosinophilic response." (PMID 18315837, 2008). "None of the well-defined asthma/inflammatory genes (Il1b, Il4, Il10, Il13, Il6, Tnfa, Infg, Tgfb1) are differentially expressed, although they connect many of the genes that are." (PMID 18087596, 2007). "In conclusion, our findings suggest that cesarean section leads to abnormal neonatal immune responses (increased secretion of IL-13 and IFN-γ) that may precede the development of asthma and atopy." (PMID 17002791, 2006). "Finally, the data presented emphasize IL-13 and TNF-α as potential therapeutic targets for treating RSV induced-asthma." (PMID 16893457, 2006). "Growing evidence shows that interleukin 13 (IL-13) may play an essential role in the development of airway inflammation and bronchial hyper-responsiveness (BHR), two defining features of asthma." (PMID 15661077, 2005). "For example, genes in the 5q31-5q33 region code for Th2-type cytokines (IL-4, IL-13, which regulate B cell heavy-chain class-switching to IgE production) and ADRB2 (which mediates airway smooth muscle relaxation and protects against bronchial hyperreactivity)." (PMID 15339344, 2004). "Asthma accompanied by Type 2 inflammation primarily involves the stimulation of Th2 cells and Type 2 innate lymphoid cells (ILC2) in response to allergens and viruses, leading to the secretion of Type 2 cytokines including IL‐4, IL‐13, and IL‐5 (interleukin‐5)." (PMID 41568067, 2026). "Since both IL-4 and IL-13 contribute to a positive feedback loop that promotes TSLP expression, inhibition of their signaling by dupilumab may help mitigate inflammation during virus-induced asthma exacerbations by indirectly reducing TSLP production." (PMID 41576028, 2026). "A higher IL13 drive could reasonably be anticipated in patients with comorbid atopic dermatitis, especially given that, unlike asthma, this condition has biologics targeting only IL13 specifically approved for treatment." (PMID 40662227, 2025). "Similarly, increases in classic asthma-driving cytokines were modest (IL-4, IL-5) or absent (IL-13)." (PMID 39229121, 2025).
asthma (continued). "Second, while the IL-13 model for type 2 asthma is well accepted and reproducible, it does not capture the complex inflammatory milieu typical of the asthmatic airway, nor do our findings address nonatopic asthma." (PMID 40446022, 2025). "Despite a trend for CCL17 protein being higher in these two participants, all other macrophage responses to IL-4, IL-13, and combined IL-4/IL-13 stimulation fell within the range of responses seen in donors without asthma and did not skew the overall dataset, justifying their inclusion." (PMID 41159038, 2025). "The comorbid asthma and overweight/obesity group had a lower expression of IL-10 and IL-13 than children with asthma alone, suggesting that the expression of Th2-related inflammatory factors was higher in children with asthma but not in children with comorbidity." (PMID 40083433, 2025). "According to the DrugBank database, multiple drugs targeting IL-13 and IL-33, or carried by FABP3 to the heart, have been developed and either approved or are under investigation for conditions such as atopic dermatitis, asthma, chronic obstructive pulmonary disease and bacterial growth." (PMID 41391830, 2025). "The conclusion of the research was that asthma and COPD represent distinct inflammatory conditions that may intersect in certain patients, manifesting as a mixed inflammatory pattern, with IL-13 potentially playing a central role in regulating inflammation in these contexts." (PMID 41002723, 2025). "By mitigating airway hyperreactivity, reducing the levels of inflammatory cytokines (IL-4, IL-5 and IL-13) involved in the Th2 immune response, and enhancing Treg immune regulation (IL-10 and TGF-β1), hydrogen therapy has emerged as a promising adjunct strategy in asthma management." (PMID 41146240, 2025). "Notably, beyond the canonical Janus kinase/STAT pathway, IL-13 has been shown to activate a non-canonical PI3K/AKT cascade in allergic diseases such as asthma and atopic dermatitis." (PMID 40501685, 2025). "However, the levels of IFN-γ, IL-10, and type-2 cytokines, including IL-4, IL-5, and IL-13, were not significantly different between Sema3E KO and WT mice in the type-2 low asthma model." (PMID 40512736, 2025). "Hence, in our mouse model of asthma, major indicators relating to the asthma model (e.g., airway hypersensitivity, total serum IgE, IFN-γ, IL-4, IL-10, IL-13, and inflammatory cell count in BALF) were detected to evaluate the physiological and biochemical changes induced by the antigen (OVA)." (PMID 38674852, 2024). "The two forms of asthma phenotypes are type 2-low, characterized by non-eosinophilic inflammation, neutrophilic involvement, metabolic responses, and type 2-high IL-5 and IL-13, which are primarily eosinophilic and pathologically driven by Th2 cells that produce IL-4." (PMID 39594470, 2024). "Similarly, in a study involving patients with asthma, the administration of nemiralisib did not yield statistically significant reductions in sputum IL-5, IL-13, IL-6 or IL-8 compared to placebo." (PMID 39427187, 2024). "Thus, in contrast to the Type 2 (T2 or eosinophilic) type of asthma which was mediated by IL-4, IL-5, and IL-13, the profile of the inflammatory mediators with high levels of IL-6, CXCL8, and IFNγ after TLR stimulation mirrored that of the non-T2 endotype of asthma." (PMID 39614276, 2024). "In addition, it significantly attenuated the symptoms of asthma attacks, reduced the number of macrophages, lymphocytes, neutrophils, and eosinophils in BALF and inflammatory cytokines, including IL-1β, IL-5, IL-6, and IL-13." (PMID 38579176, 2024). "Moreover, in a murine model of asthma, CBD-X administration significantly downregulated key asthma markers such as IgE and pro-asthmatic cytokines IL-4, IL-5, and IL-13 in both blood and lung tissues, and inhibited the migration of leukocytes, eosinophils, and neutrophils to lung tissues." (PMID 39459021, 2024).
asthma (continued). "IL-4 and IL-13, as key type-2 inflammatory cytokines, could disrupt the barrier function of epithelial cells, leading to accumulation of cellular matrix proteins and EMT progress, and consequently participate in airway remodeling in asthma." (PMID 38521909, 2024). "However, using a mouse model of IL13-induced mucus hyperplasia and primary cells from asthmatics, inhibiting the heat shock protein 90 (HSP90), upregulated in asthma with geldanamycin, blocked, and even reverted, mucus hyperproduction and goblet cell hyperplasia." (PMID 38529406, 2024). "Thus, iNKT cells from allergic asthma patients express higher ACC1, FASN and PPARG levels and lower levels of a glycolysis, which is accompanied with higher levels of IL4 and IL13 than iNKT cells from healthy controls and nonallergic asthma patients." (PMID 37917548, 2023). "Eosinophilia can identify asthmatic patients who may benefit more significantly from ICS therapy, and monoclonal antibodies targeting IgE or the type 2 cytokines (IL‐4, IL‐5 and IL‐13) or alarmins (IL‐33, TSLP) benefit patients with the ‘Type‐2‐high’ phenotype of asthma." (PMID 37963721, 2023). "To determine whether IL-13-induced AHR is IL-31RA dependent, we treated both wild-type and IL-31RA-/- mice with IL-13 and assessed AHR and other pathological and molecular changes that are relevant to asthma." (PMID 38081868, 2023). "Inhibition of IL-13 yielded no reduction in airway eosinophils in 64 patients with uncontrolled asthma, however inhibition of alarmin IL-33 reduced blood eosinophil counts in 296 patients with moderate-to-severe asthma." (PMID 40980110, 2023). "The activity of Th2 cytokines maintains the epithelial responses triggered by allergens, reacting to the cytokines IL-4 and IL-13, producing chemokines such as CCL11, CCL17 and IL-8, which, in turn, attract eosinophils, neutrophils, among other cells of the Th2 profile lingering asthma symptoms." (PMID 37841931, 2023). "Specifically, in an OVA-induced murine asthma model, intranasal treatment with a polyclonal rabbit anti-ALCAM antibody at the time of OVA challenge reduced allergic symptoms, such as the leukocyte count and Th2 cytokine (i.e., IL-4, IL-5, and IL-13) levels in BAL fluid." (PMID 37514028, 2023). "In T2-high asthma, the interaction of the airway epithelium with the external exposome activates the release of specific mediators—epithelial-derived alarmins—as thymic stromal lymphopoietin (TSLP), IL-25, and IL-33, leading to the production of IL-4, IL-5, and IL-13." (PMID 37761964, 2023). "A clinical study demonstrated that a greater number of IL-13-producing T cells and IL-17A-producing CD4+ memory T cells and an increased proportion of IL-5-producing ILC2s are present in the peripheral blood of female patients with asthma compared to those in the peripheral blood of male patients." (PMID 35625578, 2022). "While B cells may not produce IL-13, they induce Th2 cells that secrete IL-13 which has pleiotropic effects in asthma pathobiology." (PMID 35359977, 2022). "The activation of ADRB2 on human peripheral blood lymphocytes enhances IL-13 production, and studies have found that ADRB2 is required for mucus metaplasia, AHR and lung inflammatory cells in asthma models, and that the prolonged use of ADRB2 blockers could relieve allergic asthma." (PMID 36389706, 2022). "In order to test whether the SP-A 10-mer was effective in a non-allergic model of asthma, we tested the SP-A peptides (10-mer) in the IL-13 challenge model." (PMID 35874703, 2022). "While such insight may not impact ongoing attempts to target IL-4 and IL-13 in treatment of asthma, it could prompt further studies into B cell-directed therapies for allergic disease." (PMID 35359977, 2022).